NSUN6 (NOP2/Sun RNA methyltransferase 6)
Diseases named in the same sentence as NSUN6 in open-access papers (continued):
Sharing a sentence is not in itself a finding about the gene and the disease.
tumor (continued). "The level of NSUN3 and NSUN6 was increased in tumor samples, whereas the level of ALYREF, NSUN5, and NSUN7 was decreased in tumor samples." (PMID 33365328, 2020). "For clinicopathological parameters, consistent with previous result, the level of NSUN3 and NSUN6 was increased in tumor samples versus normal samples." (PMID 33365328, 2020). "Similar to the result for tumor grade, the expression of all m5C regulators was elevated from pathological stage I to IV, except for NSUN6 whose expression was lowered." (PMID 33365328, 2020). "For tumor grade, all m5C regulators gradually increased from G1 to G3 except NSUN6, which showed an opposite trend of expression." (PMID 33365328, 2020). "ROC curve analysis has highlighted NSUN6’s considerable diagnostic value across different cohorts Silencing NSUN2 significantly reduces the stemness of CRC cells, and its knockdown effectively impairs tumor growth and metastasis to the liver and lungs in vivo." (PMID 40114967, 2025). "Notably, NSUN6 emerged as the most influential protective factor, followed by other tumor‐suppressive genes such as CPEB3, RCL1 and DYRK1A." (PMID 40561176, 2025). "Furthermore, the effect of NSUN6 overexpression on tumor growth was assessed in the PDX mouse model." (PMID 40589169, 2025). "The variability in the impact of NSUN6 across various cancers may arise from its differential expression in immune cells within the tumour microenvironment (TME)." (PMID 40008496, 2025). "Likewise, qRT‐PCR and western blotting assays demonstrated that NSUN6 expression was markedly lower in tumor tissues compared with peritumoral tissues from HCC patients." (PMID 40589169, 2025). "Several studies have reported tumor‐suppressive roles of NSUN6." (PMID 40561176, 2025). "However, the restoration of NDRG1 counteracted the inhibitory effect of NSUN6 downregulation on tumor growth." (PMID 38970106, 2024). "Similarly, macrophage chemotaxis assays also demonstrated increased recruitment of M2 macrophages by tumour cells after knockout of NSUN6." (PMID 37408139, 2023). "In PAAD, the decreased level of the m5C regulator NSUN6 represses tumor proliferation." (PMID 35433474, 2022). "In PAAD, the m5C writer NSUN6 has been shown to repress cell proliferation and tumor development." (PMID 35433474, 2022). "However, Nsun6-expression was also significantly lower in later pathological stages of tumours derived from high expressing tissues, and correlated with better patient survival." (PMID 33330931, 2021). "Nsun6 was significantly down-regulated in tumours derived from testis, thyroid and ovaries." (PMID 33330931, 2021). "However, NSUN6-expression levels were down-regulated in tumours when compared to normal tissues, and high NSUN6 positively correlated with patient survival rate." (PMID 33330931, 2021). "However, NSUN6 may confer cellular fitness advantages in specific environmental context, as we find NSUN6 to be higher expressed in healthy tissues than in tumours." (PMID 33330931, 2021). "Collectively, the in vitro and in vivo experiments demonstrated the inhibitory effect of NSUN6 on HCC cell proliferation and migration, as well as on tumor growth." (PMID 40589169, 2025). "The expression level of NSUN6 was significantly decreased in the TCGA‐HCC cohort, tumor tissues of HCC patients and HCC cell lines." (PMID 40589169, 2025). "Regulators with amplificated CNV tended to highly expressed in tumor samples (e.g., DNMT1, ALYREF, and NSUN5), and vice versa (e.g., NSUN7 and NSUN6)." (PMID 36389669, 2022). "Eventually, our qRT-PCR results showed that tumor tissues had higher NOP2 and NSUN6 expression levels and lower TET2 expression than normal tissues of ccRCC samples." (PMID 35309925, 2022). "Our qRT-PCR analysis revealed elevated expression levels of NOP2 and NSUN6, but decreased expression of TET2 were in the tumor tissues compared to those in the paired normal tissues of 15 ccRCC samples obtained from FPH (p < 0.05)." (PMID 35309925, 2022).
tumor (continued). "In the present study, qRT-PCR data from 15 paired FPH ccRCC samples revealed that while NOP2 and NSUN6 were upregulated, TET2 was downregulated in tumor tissues compared with those in normal tissues." (PMID 35309925, 2022). "The expression of NSUN6 was analyzed using the TCGA‐HCC cohort, as well as through quantitative real‐time reverse transcription polymerase chain reaction (qRT‐PCR) and western blotting in tumor tissues from HCC patients and various HCC cell lines." (PMID 40589169, 2025). "Meanwhile, the downregulation of NSUN6 markedly suppressed tumor growth in the CDX model with or without radiation." (PMID 38970106, 2024). "The results indicated that the suppression of NSUN6 significantly hindered tumor growth with or without radiation." (PMID 38970106, 2024). "The expression of ALKBH1 (p = 0.036), ALYREF (p < 0.001), NOP2 (p < 0.001), NSUN2 (p < 0.001), NSUN4 (p < 0.001), NSUN5 (p < 0.001), NSUN6 (p < 0.001), NSUN7 (p = 0.006), and YBX1(p < 0.001) were significantly upregulated in tumor tissues compared with the adjacent mucosa." (PMID 35281843, 2022). "To determine whether our two prognosis-related genes can reflect the status of tumor immune infiltration, we further used the Timer database to analyze the correlation of NSUN2 and NSUN6 with immune cell infiltration in TCGA." (PMID 33928086, 2021). "Considering the role of TME in tumor occurrence and development and its prognostic impact, we used three data sets (i.e., GSE114727-inDrop, BRCA_GSE110686, and BRCA_GSE114727_10X) in the TISCH database to analyze the expression of NSUN2 and NSUN6 in TME-related cells." (PMID 33928086, 2021). "However, NSUN6, TET1, TET2, and TET3 did not have significant differences in tumor vs. normal tissues." (PMID 37907576, 2023).
cancer (27 papers, 2020 to 2026). A tumor composed of atypical neoplastic, often pleomorphic cells that invade other tissues. "NSUN6 expression is downregulated in tumors, and high NSUN6 expression is associated with better prognosis in some cancers." (PMID 40370440, 2025). "NSUN6 is also involved in the development of lung cancer and other cancers and can serve as a potential therapeutic target." (PMID 41501031, 2026). "When NSUN6 expression is upregulated, the m5C modification level of tRNA increases, promoting the translation of proteins related to cancer cell proliferation and invasion." (PMID 41501031, 2026). "H&E staining indicated enhanced proliferation of HCC cells in mice in the control group, while NSUN6 overexpression resulted in varying degrees of necrosis in cancer cells." (PMID 40589169, 2025). "Employing the TCGA dataset, the mRNA expression levels of two primary mRNA m5C methyltransferases, NSUN2 and NSUN6, in 43 pairs of adjacent and cancer tissues from patients with HNSCC was investigated." (PMID 39595099, 2024). "Based on RNA sequencing data of The Cancer Genome Atlas dataset, a prediction model containing three m5C regulators, NSUN6, DNMT2, and ALKBH1, was established." (PMID 35484099, 2022). "Meanwhile, NSUN6 downregulation is associated with ECM receptor interaction, metabolism, and cell adhesion, and these pathways have been confirmed to be related to cancer." (PMID 33928086, 2021). "Cell proliferation and migration are often reciprocally controlled, and we find that NSUN6-expression enhanced migration in cancer cells." (PMID 33330931, 2021). "In this risk score signature, four genes (NOP2, NSUN4, NSUN5, and NSUN7) were cancer-promoting and NSUN6 was a cancer-suppressor gene." (PMID 32974125, 2020). "Furthermore, NSUN6 impacts the cell cycle, immune cell infiltration, and the generation of antibody‐secreting plasma cells, highlighting its multifaceted impact on cancer biology and immune modulation." (PMID 40008496, 2025). "Targeting NSUN6 through these mechanisms may represent a promising approach to improve the poor prognosis of malignant tumors." (PMID 41256854, 2025). "This highlights the cancer type-dependent biological effects mediated by NDRG1.Whether the NSUN6-m5C-NDRG1 axis universally drives pan-cancer radioresistance requires." (PMID 40823093, 2025). "Furthermore, no reader has been detected to recognize NSUN6-dependent m5C sites on mRNA, which hinders further understanding of the regulatory role of NSUN6 in cell metabolism and cancer progression." (PMID 35562754, 2022). "Many studies have confirmed that NSUN2 and NSUN6 are related to cancer tumorigenesis." (PMID 33928086, 2021). "However, NSUN6 was down-regulated in at least some cancers and might be a novel biomarker predicting patient outcome." (PMID 33330931, 2021). "Thus, NSUN6 might be a novel biomarker for positive patient outcome in cancers derived from testis, ovary, thyroid, liver and brain." (PMID 33330931, 2021). "In COAD cells, NSUN6 up-regulates METTL3 expression and mediates its m5C modification, facilitating cancer progression." (PMID 41256854, 2025). "The expression of Nop2/Sun domain family member 6 (NSUN6), an RNA m5C methyltransferase, is correlated with the prognosis of various cancers." (PMID 40589169, 2025). "In lung cancer, NSUN6 regulates the expression of NM23-H1, promoting cancer cell proliferation, migration, and EMT." (PMID 41256854, 2025). "Existing basic experiments indicate that NOP1, NSUN2, NSUN3, and NSUN4 predominantly promote the majority of cancers, while NSUN5, NSUN6, and NSUN7 demonstrate context-dependent effects—promoting some cancers but inhibiting others." (PMID 41462962, 2025). "IHC data from the HPA online database also demonstrated that the protein levels of NSUN6 and ALYREF were more highly expressed in cancer tissues than in normal tissues." (PMID 35281843, 2022).
cancer (continued). "With respect to the two m5C-related regulators (NSUN6 and ALYREF) identified in our results, there have been some studies on cancer and related mechanisms." (PMID 35281843, 2022). "In addition, dysregulated expression of m5C-related enzymes such as NSUN6, NSUN2, and ALYREF has been reported in several cancers." (PMID 38970106, 2024). "Functional assays confirmed that these compounds effectively suppressed the catalytic activity of recombinant NSUN2 without affecting NSUN6, and stereoselectively disrupted the interaction between NSUN2 and tRNA in cancer cells, leading to a global reduction of tRNA m5C levels." (PMID 41256859, 2025).
immune dysfunction (1 paper, 2023). "We found an association between abnormal NSUN6 and immune dysfunction." (PMID 37408139, 2023).
NSUN6 also shares sentences with these, for which no sentence is quoted: esophageal squamous cell carcinoma (2 papers); Alzheimer disease (1); atherosclerosis (1); autoimmune disease (1); brain injury (1); dementia (1); infection (1); lung adenocarcinoma (1); ovarian carcinoma (1); Sepsis (1); testis cancer (1); thyroid cancer (1); urothelial bladder carcinoma (1).